IL33 (interleukin 33)
Diseases named in the same sentence as IL33 in open-access papers (continued):
Sharing a sentence is not in itself a finding about the gene and the disease.
allergic asthma (continued). "In fact, they found significant correlations between plasmatic components of the IL-33/ST2 axis and IL-31 in both allergic rhinitis patients and those with concomitant allergic asthma." (PMID 31766607, 2019). "Recently, the importance of IL-33/ST2 axis has been recognized in the trigger and maintenance of allergic asthma." (PMID 29302700, 2018). "In people with allergic asthma, RV-activated ST2+ innate lymphoid cells (ST2+ILC) were the predominant source of IL-33 augmented IL-13 release." (PMID 30174671, 2018). "IL-33 accelerates the maturation of HPC and modulates their migration into airways in allergic asthma." (PMID 29859068, 2018). "Due to their substantial role in development of type 2 immune responses in allergic asthma, it is surprising that ST2+ILC have the ability to produce IFNγ in response to IL-33 in healthy individuals." (PMID 30174671, 2018). "In non-allergic asthma, the airway inflammation was mediated by group 2 innate lymphoid cells (ILC2), a class of non T and non B cells that activated by epithelial-derived IL-25 or IL-33." (PMID 39342146, 2024). "Thus, we treated BMDMs with various allergic asthma-related cytokines, including TSLP, IL-33, IL-13, and IL-4." (PMID 38177117, 2024). "Therefore, local allergen stimulation produces IL-33 and drives the activation of ILC2, leading to eosinophilic inflammation, which is an important mechanism of allergic asthma." (PMID 38082335, 2023). "In addition to Th2 cells in allergic asthma, ILC2 can also produce type 2 cytokines under the activation of IL-33 and play a key role in the increased expression of ST2." (PMID 38082335, 2023). "MUC5B, ORMDL3, MUC5AC, CHI3L1, CLCA1, and IL-33 display a distinctly high non-specific relationship with allergic and non-allergic asthma." (PMID 33936056, 2021). "Without being involved in the baseline HDM-induced allergic asthma, IL-1β signalling was required to induce neutrophil chemotactic factors, IL-33, and Muc5ac expression at viral stimulus-induced exacerbation." (PMID 29361942, 2018). "IL17A, IL33, and IFNγ levels were significantly elevated in allergic and nonallergic asthmatics when compared to control, whereas IL5 levels were elevated only in patients with allergic asthma when compared to control." (PMID 30306094, 2018). "Our data also indicate that the IL-33/ST2 axis is not involved in the TSLP-mediated model of airway inflammation and that IL-33 is not a general therapeutic target to prevent the allergic asthma once AD develops." (PMID 28490737, 2017). "In this study, we investigated the role of TG2 in the pathogenesis of allergic asthma, particularly whether TG2 affects initial activation signaling by inducing IL-33 and downstream molecules leading to Th2 differentiation against antigens." (PMID 23496815, 2013). "The IL-33/ST2 axis, known to influence these Th2 cell types including mast cells, macrophages and eosinophils, has been recognized in modulating disease pathologies such as anaphylaxis and allergic asthma." (PMID 21851604, 2011). "In addition, IL-33 elevation is found in allergic asthma, and DNT cells ameliorated allergic asthma may partially by IL-33-induced expansion." (PMID 37019882, 2023). "Furthermore, IL-33 and its receptor, ST2, are required for cGAMP-induced allergic inflammation in the lung, which may be novel therapeutic targets for allergic asthma." (PMID 37081450, 2023). "We evaluated the levels of IL-33, IL-25 and TSLP, which are the upstream cytokines of ILC2s, in mice BALF when the airway epithelium was exposed to allergens to confirm whether Renifolin F inhibited OVA-induced allergic asthma by acting on ILC2s in mice." (PMID 35744915, 2022). "Activated platelets secrete IL-33, Dkk-1, and 5-HT or overexpress CD40L on the cell surfaces to induce Type 2 immune response or interact with TSLP-stimulated myeloid DCs through the RANK-RANKL-dependent manner to tune the sensitization stage of allergic asthma." (PMID 34440807, 2021).
allergic asthma (continued). "We extracted total RNA from the lung tissue of mice from both the control and the F2-administered groups in the allergic asthma model and examined the changes in the Th2 cytokines IL-4, IL-5, and IL-13, eosinophil-recruiting chemokine CCL11 and allergic asthma-related cytokine IL-33 using RT-qPCR." (PMID 34576124, 2021). "Furthermore, several studies concerning the direct sensitization of HDM have indicated that various factors, such as IL-21 from CD4+ T cells, IL-33 from inflammatory monocytes, TLR4-dependent inflammation, and IRF3 signals, participate in mouse models of allergic asthma." (PMID 31616416, 2019). "This study aimed to investigate the effects of IL-33 on rhinovirus (RV)-induced immune responses by circulating leukocytes from people with allergic asthma, and how this response may differ from non-allergic controls." (PMID 30174671, 2018). "Thus, cGAMP functions as a type 2 adjuvant in the lung and can promote allergic asthma in manners that dependent on the intracellular STING/TBK1/IRF3/7 signaling pathway and the resultant intercellular signaling pathway via IL-33 and ST2 might be a novel therapeutic target for allergic asthma." (PMID 31616416, 2019).
COVID-19 (94 papers, 2020 to 2025). A disease caused by infection with severe acute respiratory syndrome coronavirus 2. "IL-21 is produced by follicular helper CD4+ T-cells that sustain B-cell functions, while IL-33 levels are associated with exacerbated pulmonary inflammation in COVID-19." (PMID 40573439, 2025). "Acute COVID-19 was associated with marked elevations in nearly all pro-inflammatory markers, whilst eleven markers (namely IL-1β, IL-2, IL-6, IL-10, IL-18, IL-23, IL-33, TNF-α, IP-10, G-CSF and YKL-40) were associated with disease severity." (PMID 37063871, 2023). "Our findings confirm a defined cytokine signature in severe COVID-19 (with elevated IL-2, IL-6, TNFα, IL-1β and IL-10), and add further evidence to the role of IP-10, G-CSF and IL-33 in the cytokine milieu associated with severe COVID-19." (PMID 37063871, 2023). "Multinomial logistic regression analysis was performed to assess the significance of IL-22 and IL-33 as factors associated with COVID-19 risk." (PMID 36875710, 2023). "Higher concentrations of IL-22 and IL-33 were associated with an increased risk of COVID-19 (IL-22: OR = 17.80 [95% CI: 6.48–48.90], p = 0.001); IL-33: OR = 19.0 [95% CI: 7.4–48.6], p = 0.001)." (PMID 36875710, 2023). "Our study examined the association between serum calpain 1 activity and IL-33 concentration in patients with COVID-19 ARDS." (PMID 37509486, 2023). "Our data corroborate the previously reported increase in antiviral/proinflammatory cytokines IFN-α, TNF, IFN-γ IL-1, IL-6, IL-8, IL-17, and IL-33 in COVID-19, confirming the association between high IL-6 levels and disease severity." (PMID 37174682, 2023). "Proteins that were decreased in abundance in fatal COVID-19 included the epithelial damage-associated molecular pattern IL-33, IL-1 receptor-associated kinase-1 (IRAK1), and the lymphocyte receptors CD5 and CD6." (PMID 34710339, 2022). "Analyses of cytokines have shown that serum levels of IL-1β, IL-6, IL-10, IL-23, IL-33 and Gal-1 are in significant positive association with increased COVID-19 severity." (PMID 35075140, 2022). "Recent studies have shown that serum IL-33 is upregulated in COVID-19 patients and is strongly associated with poor outcomes." (PMID 36362440, 2022). "Serum levels > 332.08 pg/mL of IL-33 were considered a factor related to the risk of increased severity of COVID-19." (PMID 36498859, 2022). "Our results also illustrated that the serum levels of IL-1β, TNFα, IL-6, IL-12, IL-23, and IL-33 are risk factors associated with COVID-19 severity." (PMID 34917631, 2021). "Also, COVID-19 can cause immunosuppression or cytokine release, which can increase the risk of fungal infections with increased IL-18, IL-17, IL-33, neutrophils, monocytes, and basophils." (PMID 38747876, 2024). "To explore the mechanisms of decreased expression of PD-1 in CD4+ and CD8+ T cells from convalescent COVID-19 patients, we measured plasma cytokines associated with PD-1 expression, including IL-2, IL-6, IL-7, IL-10, IL-12p70, IL-33, IFN-γ and CCL19/MIP-3, by Luminex." (PMID 38424104, 2024). "However, type 2 cytokines such as IL-4, IL-13, and IL-33 have also recently been found to be associated with severe COVID-19 along with highly abundant type 2 innate lymphoid cells (ILC2s) in the mucosa (23, –, 28)." (PMID 37937994, 2023). "Focusing on the single nucleotide polymorphisms (SNPs) of IL-33, we discovered a significant inverse association between IL-33 SNP rs3939286 and COVID-19 severity, which meant that carriers of the minor genotype were found to be protected from developing more severe forms of COVID-19." (PMID 37761861, 2023). "Additionally, IL-33 has been linked to lung injury, pulmonary viral infections, and chronic lung diseases, indicating a potential association between elevated IL-33 levels and the severity of respiratory manifestations observed in COVID-19 patients." (PMID 37761861, 2023).
COVID-19 (continued). "It has been well documented that ESR and GLR are inflammatory markers associated with the pathogenesis of COVID-19, and IL-22 and IL-33 may represent additional inflammatory markers associated with the development of mild/moderate SARS-CoV-2 infection." (PMID 36875710, 2023). "However, the effects of IL-33 in COVID-19 and the underlying mechanisms remain to be fully elucidated." (PMID 36362440, 2022). "In COVID-19 patients, increased IL-33 serum levels were associated with poor outcomes." (PMID 35464491, 2022). "Our result revealed a significantly higher systemic IL-33 concentration in patients with severe COVID-19, positive association between IL-33 and innate immunity mediators, and clinical parameters of COVID-19, suggesting the important role of this cytokine in the progression of COVID-19." (PMID 34917631, 2021). "The alarmin cytokine IL-33 may also play a detrimental role in severe COVID-19 cases through expanding the pathogenic T cells, inducing hyperinflammation, and promoting the pro-fibrotic type 2 innate immune cells." (PMID 34054828, 2021). "Serum levels greater than 332.08 pg/ml of IL-33 are associated with increased severity of COVID-19, indicating that IL-33 could be used as a prognostic biomarker in patients with a diagnosis of COVID-19." (PMID 34917631, 2021). "To our knowledge, we are the first group to demonstrate an association between IL-33 levels and outcome in hospitalised patients with COVID-19, and this may have particular translational relevance in the context of the ACCORD2 study." (PMID 32962703, 2020). "Excess release of IL-33 may drive dysregulated hyper-inflammation in severe acute respiratory syndrome coronavirus 2 infection; IL-33 levels are increased in patients with COVID-19 and are associated with disease severity." (PMID 37868151, 2023). "Moreover, a minor allele within the IL-33 gene (rs3939286) was found to be associated with a protective effect against severe COVID-19 (p < 0.05), and minor alleles of the TSLP gene (rs2289276 and rs13806933) were found to significantly reduce TSLP protein levels in serum (p < 0.05)." (PMID 37761861, 2023). "However, the specific effects of IL-33 in COVID-19 and the underlying mechanisms remain elusive." (PMID 36362440, 2022). "In contrast, IL-33 was consistently reduced in both severe COVID-19 and post-acute sequelae (Long COVID)." (PMID 41157211, 2025). "Admission IL-1β, and IL-33 were significantly lower, while IL-18 was significantly higher in cases when COVID-19 became more severe, along with significantly decreased FVIII, FXIII and plasminogen." (PMID 40303405, 2025). "In severe COVID-19, elevated IL-3 and IL-33 in the lung microenvironment suggest a shift toward innate “alarmin” driven, type-2 inflammation." (PMID 41459501, 2025). "IL-33 activation has been reported in advanced COVID-19, contributing to severe lung inflammation by activating several proinflammatory cytokines such as IL-6 and TNF-α through the MyD88-MAPK-NF-kB signaling axis." (PMID 40242753, 2025). "The patients’ IL-33 levels were consistently reduced, both in severe forms of COVID-19 and in patients with long COVID." (PMID 41157211, 2025). "Intriguingly, in our current study, it has a negative correlation with several cytokines in healthy control, but with only IL-1α and IL-33 in COVID-19 patients, denoting the variable response to SARS-CoV-2 infection in different ethnicities." (PMID 38855114, 2024). "Ultra-sensitive immunoassays were developed to measure IL-33red, IL-33ox and IL-33/sST2 complexes in samples from patients hospitalised with COVID-19." (PMID 39662674, 2024). "High serum concentration of IL-33 is a marker of unfavorable COVID-19 outcome and locally produced IL-33 was demonstrated in lungs with post-COVID-19 fibrosis patients." (PMID 38664396, 2024).
COVID-19 (continued). "Thrush Candida albicans patients showed increased IL-8 (56.7 pg/mL) and IL-17 (101.1 pg/mL) concentrations, with the greatest concentration of IL-33 (200.5 pg/mL) in COVID-19, and a decrease in the level of IL-10 in patient groups compared with controls." (PMID 38747876, 2024). "IL-8 and IL-17 concentrations were highest in CTC patients, while IL-33 was higher in COVID-19 and CTC." (PMID 38747876, 2024). "We had reported increased IL-33 soluble receptor (ST2) in the serum of severe COVID-19 patients that we interpreted as a futile effort to neutralize increased circulating IL-33." (PMID 37298438, 2023). "Median IL-22 and IL-33 concentrations were significantly elevated in COVID-19 patients compared with HC (IL-22: 18.6 [IQR: 18.0–19.3] vs. 13.9 [IQR: 12.1–14.9] pg/mL, p < 0.001); IL-33: 37.8 [IQR: 35.3–43.0] vs. 24.1 [IQR: 23.0–26.2] pg/mL, p < 0.001)." (PMID 36875710, 2023). "There has been a reported association between the anxiety–depressive spectrum phenomena and IL-28A and IL-33 levels in individuals diagnosed with COVID-19." (PMID 37759873, 2023). "Significantly higher levels of total IL-33 and IL-25 were measured in the serum of COVID-19-positive patients compared to COVID-19-negative individuals." (PMID 37761861, 2023). "Stanczak and co-Workers reported that after recovery from COVID-19, individuals have persisting, circulating peripheral blood mononuclear cells (PBMCs) that produce IL-33 in response to virus-specific T cell activation, which correlates with seropositivity." (PMID 37483591, 2023). "As indicated by the area under the curve (AUC), IL-22 and IL-33 were excellent predictors of COVID-19 (AUC = 0.95 and 0.892, respectively)." (PMID 36875710, 2023). "It has been demonstrated that serum IL-33 concentrations were significantly increased in patients with severe/critical COVID-19 compared to patients with mild/moderate disease, but all severe/critical patients were over 64.5 years old and 81.8% were male." (PMID 36875710, 2023). "Thereby, the presence of hyperactivated MCs correlated with the strongly elevated levels of IL-33, ATP and MC proteases in the serum of COVID-19 patients." (PMID 38067124, 2023). "This study analyzed serum concentrations of interleukin (IL)-22 and IL-33 (pro-inflammatory and anti-inflammatory cytokines) in 90 patients with mild/moderate coronavirus disease 2019 (COVID-19) and 90 healthy controls." (PMID 36875710, 2023). "In this study, serum IL-22 and IL-33 concentrations were analyzed in patients with mild/moderate COVID-19 and compared with age-, sex- and BMI-matched HC." (PMID 36875710, 2023). "Amongst those with acute COVID-19, eleven markers significantly differed across disease severity categories: IL-1β, IL-2, IL-6, IL-10, IL-18, IL-23, IL-33, TNF-α, IP-10, G-CSF and YKL-40." (PMID 37063871, 2023). "In this context, several papers described IL-33 as an important pathophysiological factor in the development of severe forms of COVID-19." (PMID 37509486, 2023). "We conducted a multinomial regression analysis to explore potential relationships between TSLP and IL-33 SNPs and COVID-19 severity." (PMID 37761861, 2023). "The blood concentrations of the antiviral cytokine IFN-α and proinflammatory cytokines TNF, IFN-γ, IL-6, IL-8, IL-17, and IL-33 were significantly increased in COVID-19 patients both at admission and one week later, compared to healthy controls." (PMID 37174682, 2023). "Concerning the influence of TNF-α, we found higher values in the group with severe COVID-19 in terms of IgA, IL-10, IL-33, IL-28A and CD40L and lower values of IgM." (PMID 38137381, 2023). "IL-33 is the next cytokine that showed up-regulated concentrations in COVID-19 patients, very good discrimination potential between patients and HC (AUC = 0.892), and a 19.0-fold increased risk of disease." (PMID 36875710, 2023). "Several studies have reported elevated IL-33 in individuals with COVID-19, with levels increasing with greater disease severity." (PMID 37063871, 2023).